TLR8 (toll like receptor 8)
Diseases named in the same sentence as TLR8 in open-access papers (continued):
Sharing a sentence is not in itself a finding about the gene and the disease.
anemia (5 papers, 2023 to 2025). A reduction in the number of red blood cells, the amount of hemoglobin, and/or the volume of packed red blood cells. "By contrast, we identified a novel germline GOF mutation in TLR8 (p.V434L) in the pedigree that the proband suffered from anemia." (PMID 38971858, 2024). "Collectively, we identify a gene implicated in inherited anemia and a previously undescribed role for TLR8 in erythropoiesis, which could potentially be explored for therapeutic benefit in inherited anemia." (PMID 38971858, 2024). "The anemia observed in NASA patients almost certainly is due to severe chronic systemic autoinflammation rather than immune-mediated mechanisms (as occurs in patients with TLR8 mutations causing TLR7-mediated autoinflammation)." (PMID 37744344, 2023). "We discovered that expression of the endosomal ssRNA sensor human TLR8 induces fatal anemia in Sle1.Yaa lupus mice." (PMID 37495396, 2023). "As the proband was diagnosed with inherited non-hemolytic anemia and TLR8 inhibition improved erythropoiesis, we then determined whether TLR8 inhibition with CUCPT8m would have the beneficial impact on inherited anemia." (PMID 38971858, 2024). "Furthermore, patients with mosaic TLR8 gain-of-function present immunodeficiency, inflammation, anemia, and BM failure." (PMID 37495396, 2023). "Increased TLR8 signaling also impairs erythropoiesis by inducing inflammatory inhibition of EPO responsiveness, contributing to anemia in many patients." (PMID 41369391, 2025). "Additional case reports describe severe autoinflammation, autoimmune cytopenias and dysregulation of TLR8/TLR7 signaling, while experimental work demonstrates that overexpression or hyperactivation of human TLR8 can induce inflammatory bone-marrow failure and anemia." (PMID 41369391, 2025).
basal cell carcinoma (5 papers, 2018 to 2023). A carcinoma involving the basal cells. "Imiquimod, a ligand for TLR7 and TLR8, is a potent immune activator also used for the treatment of virus-associated skin abnormalities as well as (pre)cancerous skin lesions and superficial basal cell carcinomas." (PMID 30613363, 2018). "IMQ is an agonist of TLR7 and TLR8 and is approved for the treatment of genital warts, superficial basal cell carcinoma, and actinic keratosis." (PMID 35116069, 2022). "Imiquimod is a TLR7 (and TLR8 in humans) agonist used for the treatment of superficial basal cell carcinomas, actinic keratoses and some viral skin infections." (PMID 36477177, 2022).
bone marrow failure (5 papers, 2022 to 2025). "A focused review has highlighted TLR8-GOF as an “interface” disorder between bone-marrow failure and IEIs, and summarizes current therapeutic experience including antimicrobial prophylaxis, immunoglobulin replacement, immunosuppressive drugs and HSCT." (PMID 41369391, 2025). "Mosaic and germline TLR8-GOF variants define a childhood-onset IEI characterized by lymphoproliferation, neutropenia, recurrent infections, B- and T-cell abnormalities and, in some patients, bone-marrow failure." (PMID 41369391, 2025). "In this article, we will share lessons that patients with gain-of-function defects in Toll-like receptor 8 (TLR8-GOF) can teach us about the interface between bone marrow failure (BMF) disorders and inborn errors of immunity (IEI), subsequently referred to as “Interface Disorders”." (PMID 36119097, 2022).
bronchiolitis (5 papers, 2010 to 2017). Inflammation of the bronchioles characterized by swelling of the bronchioles and mucus accumulation. "Nucleic acid-sensing PRRs including RIG-1, MDA-5, TLR-8 were found to be associated with acute bronchiolitis in infants." (PMID 23626859, 2013). "Both findings implicate impaired early innate immune response in infants with RSV-bronchiolitis linked to lower TLR8 expression and subsequent lower TNF-α release, that has been associated with acute RSV infection." (PMID 20946625, 2010). "Our study was an exploratory study on the possible association between the TLR7 rs179008, TLR8 rs4207992, TLR9 rs187084 or TLR10 rs4219009 gene polymorphisms and characteristics of bronchiolitis in early infancy or post-bronchiolitis outcomes." (PMID 27498757, 2016). "TLR8 expression levels in monocytes from 10 retested infants in the convalescent phase (4-6 weeks after first sampling) were significantly higher than from infants with bronchiolitis (up to 7 days of disease onset) during acute RSV infection." (PMID 20946625, 2010). "The aim of the present study was to complement this exploratory study series by evaluating whether the TLR7 rs179008, TLR8 rs2407992, TLR9 rs187084 and TLR10 rs4129009 polymorphisms are associated with the presence, clinical characteristics and viral etiology of bronchiolitis in early infancy." (PMID 27498757, 2016). "The aim of this exploratory study was to evaluate whether there are associations between TLR7 rs179008, TLR8 rs2407992, TLR9 rs187084 or TLR10 rs4129009 polymorphisms and viral findings, clinical characteristics or subsequent wheezing in infants with bronchiolitis." (PMID 27498757, 2016).
head and neck squamous cell carcinoma (5 papers, 2015 to 2025). A squamous cell carcinoma that arises from any of the following anatomic sites: lip and oral cavity, nasal cavity, paranasal sinuses, pharynx, larynx, and salivary glands. "The goal of this work is to examine the role of TLR8 expression/activity in head and neck squamous cell carcinoma (HNSCC) to facilitate the prediction of responders to VTX-2337-based therapy." (PMID 33452311, 2021). "To decipher the combinatory mode of action of TLR8 agonism and PD-1 blockade, we employed a unique, open-label, phase 1b pre-operative window of opportunity clinical trial (NCT03906526) in head and neck squamous cell carcinoma (HNSCC) patients." (PMID 39697344, 2024). "Imiquimod (Aldara) is FDA approved and used to treat patients with melanoma and VTX-2337 (a TLR8 agonist) has been used in phase II clinical studies to treat patients with head and neck squamous cell carcinoma (HNSCC) as well as cancers of the reproductive tract and peritoneal cavity." (PMID 26101781, 2015). "Notably, in clinical investigations of head and neck squamous cell carcinoma (HNSCC), multiple studies have evaluated TLR8/9 agonists—including the TLR8 agonist motolimod and TLR9 agonists SD-101, IMO-2055, and EMD1201081—in combination with cetuximab or PD-1 inhibitors." (PMID 41488647, 2025). "The small TLR8 agonist motolimod (VTX-2337) exhibits antitumor activity in recurrent or metastatic head and neck squamous cell carcinoma (HNSCC) by stimulating natural killer cells and enhancing antibody-dependent cell-mediated toxicity." (PMID 34422051, 2021).
Immunodeficiency (5 papers, 2012 to 2025). Failure of the immune system to protect the body adequately from infection, due to the absence or insufficiency of some component process or substance. "There was a recent report of mosaic TLR8 gain-of-function variants that cause immunodeficiency." (PMID 37325673, 2023). "Moreover, differences in PWH with regard to the viral reservoir, including diverse mechanisms underlying latency and the level of HIV immune dysfunction may explain the variable effects of TLR8 and RLR agonists on the viral reservoir." (PMID 40141220, 2025). "Our findings demonstrate that the induction of these cytokines can be synergistically increased by combining SMACm with TLR8 agonists, even in PBMC from PWH albeit to a lesser extent due to HIV-associated immune dysfunction." (PMID 40141220, 2025). "Together with the decline in CD4+ T cell numbers, the downregulation of TLR8, IL-8 and HLA-DOA expressed on macrophages/dendritic cells and B cells, respectively, suggests generalized immune dysfunction that can in due course lead to immune exhaustion." (PMID 22511950, 2012). "Similarly, TLR8 agonists with SMACm also induced a pro-inflammatory cytokine response in PBMC from PWH, albeit to a lesser extent, likely due to immune dysfunction observed with chronic infection in untreated PWH." (PMID 40141220, 2025).
pancreatic cancer (5 papers, 2015 to 2024). "We conclude that inflammation-mediated progression, tumor survival, metastatic potential and mediation of chemoresistance are closely associated with TLR7 and TLR8 expressing pancreatic cancer cells." (PMID 26134824, 2015). "Notably, COX-2 expression was indeed upregulated in our investigated patient tumors and was associated with TLR7 and TLR8 positivity in specimens of pancreatic cancer and after stimulation of human PANC1 cancer cells." (PMID 26134824, 2015). "Whether intracellular TLR7 and TLR8 expression, known to be associated with single stranded RNA (virus) infection in this context may be associated with recognition of pathogenic viruses in the investigated human pancreatic cancers remains speculative." (PMID 26134824, 2015). "Compared to earlier stages and chronic pancreatitis, the expression of TLR7/TLR8 was increased in stage I-IV pancreatic cancer, which was upregulated in a stage-dependent manner in advanced tumors." (PMID 36476317, 2022). "Functional analysis in human pancreatic cancer cells point to a significant role of both TLRs in chronic inflammation-mediated TLR7/TLR8 signaling leading to tumor cell proliferation and chemoresistance." (PMID 26134824, 2015). "Increased COX-2 expression together with TLR7 and TLR8 positivity in pancreatic cancer cells was detected (top and below right, and B, respectively)." (PMID 26134824, 2015). "Our data demonstrate a stage-dependent upregulation of both TLR7 and TLR8 expression in pancreatic cancer." (PMID 26134824, 2015). "In the present study, we determined the role of both TLR7 and TLR8 expression and signaling in tumor cell proliferation and chemoresistance in pancreatic cancer." (PMID 26134824, 2015). "We showed that stimulation of both receptors TLR7 and TLR8 in pancreatic cancer cells results in increased tumor cell proliferation and reduced chemosensitivity." (PMID 26134824, 2015). "Expression of TLR7/TLR8 in UICC stage I–IV pancreatic cancer, chronic pancreatitis, normal pancreatic tissue and human pancreatic (PANC1) cancer cell line was examined." (PMID 26134824, 2015). "In general, TLR7 expression of pancreatic cells in all analyzed subjects with pancreatic cancer and with chronic pancreatitis was more intense than TLR8." (PMID 26134824, 2015). "We characterized the expression of TLR7 and TLR8 in several purchased human pancreatic cancer cell lines." (PMID 26134824, 2015). "To analyze the impact of the intracellular TLR7 and TLR8 expression in mediating inflammation in pancreatic cancer cells we first examined in the present study their expression in human tissues from primary pancreatic cancers." (PMID 26134824, 2015). "TLR7 and TLR8 expression in pancreatic cancer, chronic pancreatitis, and normal pancreatic tissue was analyzed by immunohistochemistry in pancreatic tissue from patients with pancreatic cancer (UICC II and UICC III, n=48), chronic pancreatitis (n=8) and in normal pancreas (n=8)." (PMID 26134824, 2015). "To analyze whether inflammation in pancreatic cancer was associated with TLR7 and TLR8 expressing cancer cells, we dissected the expression of COX-2 in the pancreatic tumor cells by immunohistochemical staining and western blot analysis." (PMID 26134824, 2015). "Interestingly, in the present study in pancreatic cancer we observed that TLR7 or TLR8 stimulation increased tumor cell survival and resistance to the chemotherapeutic substance 5-fluorouracil." (PMID 26134824, 2015). "It was found that miR-21 in lung and pancreatic cancer cell-derived exosomes could bind to TLR8 on human muscle cells or TLR7 (homologous to TLR8 in humans) on mouse muscle cells to activate the Jun N-terminal kinase (JNK) pathway and induce apoptosis of muscle cells, thereby causing muscle atrophy." (PMID 38689293, 2024).
pancreatic cancer (continued). "Functional analysis in human pancreatic cancer cells points to a significant role of both TLR7 and TLR8 in chronic inflammation-mediated signaling transduction, leading to tumor cell proliferation and chemoresistance." (PMID 36476317, 2022). "In contrast to tumor cells derived from our patients with pancreatic cancer, acquired tumor cell lines expressed only very low levels of TLR7 and TLR8." (PMID 26134824, 2015). "In the present study, we analyzed the expression of TLR7, TLR8, NF-κB and COX-2 in pancreatic cancer at different UICC stages and compared with chronic pancreatitis and healthy controls." (PMID 26134824, 2015). "We observed that tumor cells in pancreatic cancer strongly expressed stage-dependent TLR7 and TLR8." (PMID 26134824, 2015). "This includes Bcl-2 in PANC1 pancreatic cancer cells stimulated with an agonist for TLR7 and TLR8." (PMID 26134824, 2015). "Indeed TLR7, TLR8 and CD34 were positively expressed in pancreatic cancer and pancreatic cells from chronic pancreatitis cells, but not or at very low levels in normal pancreatic cells." (PMID 26134824, 2015). "Thus, intracellular TLR7 and TLR8 signaling pathways in TLR7+ and TLR8+ expressing pancreatic cancer cells may have the potential to sustain cancer progression." (PMID 26134824, 2015).
pneumonia (5 papers, 2022 to 2025). An acute, acute and chronic, or chronic inflammation focally or diffusely affecting the lung parenchyma, caused by an infection in one or both of the lungs (by bacteria, viruses, fungi, or mycoplasma.). "In Baladi goats with pneumonia and healthy control group, PCR-DNA sequencing revealed SNPs linked to pneumonia susceptibility and resistance in immunological genes (SLC11A1, CD-14, CCL2, TLR1, TLR7, TLR8, TLR9, defensin, SP110, SPP1, BP1, A2M, ADORA3, CARD15, IRF3, and SCART1)." (PMID 40221769, 2025). "The immune genes’ mRNA levels in goats (SLC11A1, CD-14, CCL2, TLR1, TLR7, TLR8, TLR9, defensin, SP110, SPP1, BP1, A2M, ADORA3, CARD15, IRF3, and SCART1) varied between the healthy and infected goats with pneumonia." (PMID 40711280, 2025). "Significant results were obtained when comparing the samples obtained from individuals with pneumonia before the spread of SARS-CoV-2 and from the controls for rs5743551 (TLR1) and rs3764880 (TLR8)." (PMID 36611413, 2022). "Through PCR-DNA sequencing in Baladi goats with and without pneumonia, SNPs linked to pneumonia susceptibility and resistance were discovered in the immunological (SLC11A1, CD-14, CCL2, TLR1, TLR7, TLR8, TLR9, defensin, SP110, SPP1, BP1, A2M, ADORA3, CARD15, IRF3, and SCART1) genes." (PMID 40711280, 2025). "The levels of immunological genes (SLC11A1, CD-14, CCL2, TLR1, TLR7, TLR8, TLR9, defensin, SP110, SPP1, BP1, A2M, ADORA3, CARD15, IRF3, and SCART1) vary in goats with and without pneumonia." (PMID 40221769, 2025). "Real-time PCR was conducted to quantify the expression levels of immunological markers (SLC11A1, CD-14, CCL2, TLR1, TLR7, TLR8, TLR9, β defensin, SP110, SPP1, BP1, A2M, ADORA3, CARD15, IRF3, and SCART1) in Baladi goats with and without pneumonia resistance." (PMID 36977224, 2023).
prostate carcinoma (5 papers, 2021 to 2024). A carcinoma that arises from epithelial cells of the prostate gland. "Lactate modulates CD4+ T-cell polarization and induces an immunosuppressive tumor environment, which sustains the progression of prostate carcinoma via the Toll-like receptor 8 signaling pathway." (PMID 39830505, 2024). "Lactate regulates CD4+ T cell polarization and induces immunosuppression to promote prostate cancer progression through the TLR8/miR21 axis." (PMID 35223996, 2022). "In prostate cancer, in contrast, CAFs drive the polarization of naïve CD4 + T cells from the Th2 to Th1 phenotype by stimulating the miR21/Toll-like receptor 8 (TLR8) axis through the release of lactate." (PMID 34635121, 2021).
actinic keratosis (4 papers, 2018 to 2023). A precancerous lesion of the skin composed of atypical keratinocytes. "IMQ is used for treating actinic keratosis and genital warts through an agonistic effect on Toll-like receptor (TLR) 7 and TLR8." (PMID 29615641, 2018).
allergic rhinitis (4 papers, 2012 to 2017). Inflammation of the nasal mucous membranes caused by an IgE-mediated response to external allergens. "Moreover, it was recently reported that nasal administration of a TLR8 agonist (i.e. VTZ-1463) improved symptoms of allergic rhinitis." (PMID 22726593, 2012).
Arthritis (4 papers, 2017 to 2023). Inflammation of a joint. "TLR8 has been implicated in the pathogenesis of arthritis, as its overexpression causes spontaneous inflammatory arthritis in mice." (PMID 28245863, 2017). "Furthermore, when overexpressing human TLR8 in mice, researchers found that huTLR8 would promote the exacerbation of arthritis, and the levels of huTLR8 were related to proinflammatory cytokines in mice joints." (PMID 35473522, 2023). "Transgenic mice expressing high levels of human TLR-8 spontaneously develop arthritis while mice expressing low levels of TLR-8 do not." (PMID 31867014, 2019).
atopic dermatitis (4 papers, 2014 to 2021). "In our previous study, TLR8 was considered as one of the markers with significant changes in macrophages of the atopic dermatitis-like inflammatory response (data not shown)." (PMID 34442794, 2021).
diabetes (4 papers, 2017 to 2024). "Interestingly and in contrast to these findings, our results showed a reduced gene expression of Tlr5 and Tlr8 8 weeks after STZ-induced diabetes in the heart." (PMID 29538462, 2018). "In the GC group, there was a significant correlation between duration of diabetes and monocyte RANTES (r = −0.715, p = 0.05) and TLR8 (r = 0.741, p = 0.04) mRNA, and neutrophil TLR2 mRNA (r = −0.838, p = 0.01)." (PMID 28794498, 2017).
glioma (4 papers, 2019 to 2025). A benign or malignant brain and spinal cord tumor that arises from glial cells (astrocytes, oligodendrocytes, ependymal cells). "We identified AD- and glioma-associated miR-9-5p, miR-132-5p, miR-340-3p, miR-30e-3p, miR-501-3p, and let-7b as ligands for human TLR7 and TLR8." (PMID 41322409, 2025). "While several studies report effects of TLR3, TLR7 and TLR8 signaling in gliomas, their overall roles remain context dependent and incompletely defined while the functions of TLR5 and TLR10 are largely underexplored." (PMID 41157253, 2025). "Up to date, TLR2, TLR3, TLR4, TLR7, and TLR9 have been intensely studied in glioma, while less or missing information is available regarding the mechanisms of TLR1/TLR6 (dimerizes with TLR2), TLR5, TLR8 (dimerizes with TLR7), and particularly TLR10." (PMID 34715891, 2021). "Moreover, TLR2, TLR3, TLR4, TLR7, TLR8, and TLR9 have emerged as critical modulators of glioma biology." (PMID 41157253, 2025). "Similarly, another study found that TLR7/TLR8 is not expressed in the glioma rat model CNS-1; however, the activation of TLR7/8 by R848 alone was sufficient to cause rejection of the smaller established glioma in CNS-1." (PMID 31240216, 2019). "The impact of TLR3, TLR5, TLR7, TLR8, and TLR10 signaling in glioma development is not fully elucidated." (PMID 34715891, 2021).